SLAMF6 (SLAM family member 6)
Diseases named in the same sentence as SLAMF6 in open-access papers (continued):
Sharing a sentence is not in itself a finding about the gene and the disease.
tumor (continued). "Co-administering anti-SLAMF6/CD352 monoclonal antibody with the Bruton tyrosine kinase inhibitor, ibrutinib, synergized to efficiently eliminate the tumor cells in the spleen, bone marrow, liver, and the peritoneal cavity." (PMID 38612827, 2024). "Taken together, anti-SLAMF6/CD352 both effectively corrected CD8+ T-cell dysfunction and had a direct effect on tumor progression." (PMID 38612827, 2024). "Compared with CD4+ T cells in spleen, tumor‐infiltrating CD4+ T cells lost expression levels of TCF‐1 and SLAMF6 in a melanoma model, indicating that tumor‐infiltrating CD4+ T cells seem to be a transitory or terminal exhausted T cells." (PMID 37829505, 2023). "Both ncM and intM were enriched in transcripts for SLAMF6, reported to boost IFN-γ production and cytolytic anti-tumor activity of human CD8 T cells in vitro." (PMID 35967310, 2022). "In summary, we have shown that SLAMF6 is a constitutive inhibitory immune receptor; in its absence, CD8+ T cells acquire stronger reactivity against tumor cells." (PMID 32122464, 2020). "Nonetheless, checkpoint blockade still resulted in significant downregulation of TCF-1 and SLAMF6, reduced SLAMF6+ TSL numbers, reduced imputed TCR affinity, as well as a similar partial inhibition of tumour growth as seen in non-CD4-depleted mice." (PMID 41299179, 2026). "Similarly, electrotransfection of pCAGGS-Notch2MUT into LLC tumor-bearing mice reversed anti–PD-L1 unresponsiveness and significantly promoted CD8+ TIL infiltration and 4-1BB expression on SLAMF6+ CD8+ TILs in LLC tumors." (PMID 41348109, 2026). "Total SLAMF6+ TSL in the control group declined substantially from day 12 to day 19.5, probably due to diminished antigen presentation in the tdLN during late tumour growth." (PMID 41299179, 2026). "Thus, clustering SLAMF6+ TSL cell niches is a distinct spatial feature that occurs even with natural precursor frequencies and with different tumour and vaccine models." (PMID 41299179, 2026). "Macrophages with suppressed SLAMF6 levels were able to reduce HCC cell migration and invasion and could prevent tumor growth." (PMID 38476238, 2024). "However, on week 4, tumors treated with Pmel-1 ACT escaped control and grew again in six of the seven animals, whereas mice receiving Pmel-1 x SLAMF6 -/- ACT survived longer, and three of the seven treated mice remained tumor-free for over 80 days." (PMID 32122464, 2020). "This homodimerization reduces NK-cell activity toward hematopoietic (i.e. SLAMF6+) cells while enhancing activity toward non-hematopoietic (SLAMF6−) tumor cells." (PMID 31360302, 2019). "However, to date, there has been no study investigating the impact of intra-tumoral SLAMF6 expression on immunological status of the tumor and clinical outcome." (PMID 38287061, 2024). "PTPN2 deletion in CD8+ T cells also boosts the generation, proliferation, and cytotoxicity of Tim-3+ terminally exhausted subpopulation without altering the Slamf6+ progenitor exhausted subpopulation, which enhances anti-tumor responses and improves tumor control." (PMID 36077422, 2022). "In particular, SLAMF6 and SLAMF1 expression in TAMs was increased by LFC = 2.1 and 3.5, both p.adj < 0.0001, and CXCL13 (LFC: 6.4, p.adj < 0.0001) and CXCR5 (LFC: 1.8, p.adj = 0.001) were highly upregulated in macrophages from the tumor compared to those from a normal lung." (PMID 33918618, 2021). "Thus, we hypothesized that the expression patterns of Slamf6, Tim3, and CD39 may help discriminating Tpe from Tex among tumor-specific TILs." (PMID 32174925, 2020). "To explore the role of SLAMF6 in T cells without the confounding effects of its function in other cell types, we generated a system in which effector T cells interact with their tumor target based on specific epitope recognition and subsequently generate an immunological synapse." (PMID 32122464, 2020).
tumor (continued). "Our results showed that the adoptive transfer of SLAMF6+ PD-1+ CD8+ T cells, but not SLAMF6- PD-1+ CD8+ T cells, could promote DPVB-mediated tumor regression by enhancing the cytotoxic capacity of CD8+ T cells." (PMID 38001101, 2023).
cancer (20 papers, 2008 to 2025). A tumor composed of atypical neoplastic, often pleomorphic cells that invade other tissues. "Loss of SLAMF6 can enhance potential of cancer elimination and it is defined as a T cell checkpoint modulator." (PMID 38997297, 2024). "SLAMF6 antibodies have previously been suggested as potential cancer therapeutics but through different mechanisms." (PMID 41044242, 2025). "To understand the dynamics of exhausted T cells, we examined the relationship between the expression of the stem-like markers Tcf7, Slamf6, Lef1, and Bach2 and the exhaustion markers across the pan-cancer dataset." (PMID 40076932, 2025). "We intended to equip CAR T cells with the soluble immunostimulatory Δ17–65 isoform 2 of SLAMF6 to expedite their anti-cancer cell functionality in an auto-stimulatory loop." (PMID 40558528, 2025). "In this study, we found that Id2 regulates the generation of Slamf6+ Texprog cells and the Texprog-to-Texterm conversion in cancer." (PMID 38287103, 2024). "TM4SF5 expression in cancer cells downregulated stimulatory ligands and receptors for NK cell cytotoxicity, including SLAMF6, SLAMF7, MICA/B, and others." (PMID 34921636, 2021). "SLAMF6 is an attractive target for the development of checkpoint inhibitors for systemic treatment of cancer and for the improvement of antitumor cellular therapies." (PMID 32122464, 2020). "One protein called SLAMF6 is found on cells from the immune system that attack and kill cancer cells." (PMID 32122464, 2020). "This is the first study to demonstrate aberrant expression of SLAMF6 in any type of cancer." (PMID 41044242, 2025). "There are differences in function of SLAMF6 among human cancers in regulating tumorigenesis." (PMID 38997297, 2024). "Furthermore, SLAMF6 can improve function of CD8+ T cells in exerting anti-cancer activity against melanoma." (PMID 38997297, 2024). "Overall, the exact mechanism of SLAMF6 in cancer cell signaling remains to be elucidated." (PMID 37251372, 2023). "Immunotherapies that suppress SLAMF6 on immune cells called killer T cells could increase immune system activity helping to treat cancers, particularly melanoma skin cancers." (PMID 32122464, 2020). "‘Progenitor exhausted’ (also referred to as ‘stem-like’) PD1+ Slamf6+ CD8 T cells are considered the main responder population in anti-PD1 blockade therapy, in both mouse models and cancer patients." (PMID 41331250, 2025). "In conclusion, we describe a completely novel immune escape mechanism in cancer, in which AML cells induce aberrant expression of the lymphocyte marker SLAMF6 and thereby inhibit T cell-mediated killing, in a process analogous to the PDL1–PD1 interaction." (PMID 41044242, 2025). "Akin to chronic viral infection and cancer systems, pop3 (KLRG1-CD62Lhi) exhibits the characteristics of stem-like progenitor CD8 T cells (high Tcf7, Slamf6, and Cxcr5 expression), whereas pop4 (KLRG1+CD62Lhi) closely resembles a transitory subset (elevated Tbx21, low Tcf1, and Tox expression)." (PMID 39975082, 2025). "Contrary to studies demonstrating beneficial effects of SLAMF6 on T cell functionality, other reports implicate SLAMF6 as a driver of T cell exhaustion, conferring a largely negative impact on T cell functionality in cancer." (PMID 40558528, 2025). "SLAMF6 is one of the signaling lymphocytic activation molecules, which can affect T cell function in regulating cancer immunity, but the role of SLAMF6 in T cell signaling is not clear yet and there are conflicting reports on whether SLAMF6 enhances or inhibits T cell activity." (PMID 37889708, 2023).
infection (10 papers, 2014 to 2025). The state of being infected such as from the introduction of a foreign agent such as serum, vaccine, antigenic substance or organism. "By d14 of infection, almost all SLAMF6+ T cells within each infection setting overlaid with population 3 with the greatest number evident in the d0–1 IFNAR-blocked mice." (PMID 40062995, 2025). "At the acute infection stage, Slamf6 exhibited a notable 3.57-fold upregulation, a regulation attributed to Gm37724." (PMID 38229193, 2024). "Blocking at the time of infection and the following day (days 0 and 1, d0–1) led to the highest increase in the frequency and the number of TCF-1+SLAMF6+ stem-like T cells, which were formed in the near absence of KLRG1+ TEFF cell differentiation." (PMID 40062995, 2025). "Seven days post-infection (PI), we observed increased frequencies of transferred OT1 cells in mice receiving PD-1+ Tim3– Slamf6+ CD39– cells compared to those receiving their CD39+ counterparts or total PD-1+ OT1 CD8 TILs, indicating their enhanced recall response and persistence." (PMID 32174925, 2020).
SLAMF6 also shares sentences with these, for which no sentence is quoted: HIV-1 infection (4 papers); pancreatic carcinoma (2); rheumatoid arthritis (2); acute myeloid leukemia (1); asthma (1); autoimmune disease (1); bacterial infection (1); cervical cancer (1); Chagas disease (1); coronary heart disease (1); glioma (1); head and neck cancer (1); influenza infection (1); latent infection (1); lung carcinoma (1); lymphoblastic acute leukemia (1); renal disease (1); thymoma (1); X-linked lymphoproliferative syndrome (1); ZIKV infection (1).